AVPR2 (arginine vasopressin receptor 2)
Description:
G protein-coupled receptor for arginine vasopressin, an antidiuretic that promotes renal water reabsorption. Ligand binding causes a conformation change that triggers signaling via guanine nucleotide-binding proteins (G proteins) and modulates the activity of downstream effectors, such as adenylate cyclase (cAMP). AVPR2 is coupled to G(s) G alpha proteins and mediates activation of adenylate cyclase activity.
Synonyms: V2R; ADHR; DIR; DIR3; DI1; NDI; NDI1
Tractability: Small molecule: an approved drug acts on it; a structure with a bound ligand is known; a high-quality ligand is known; it belongs to a druggable protein family. Antibody: UniProt places it where antibodies can reach, with high confidence; its Gene Ontology location is reachable by antibodies, with high confidence; UniProt predicts a signal peptide or a membrane-spanning region. PROTAC: a small molecule that binds it is known. Other modalities: an approved drug acts on it.
Target class: Family A G protein-coupled receptor; Vasopressin and oxytocin receptor; Short peptide receptor (family A GPCR); Membrane receptor; Peptide receptor (family A GPCR)
Chemical probes: CHEMBL2172288, CHEMBL2172289, PECAVAPTAN (high quality), VNA932
Gene: Protein-coding gene on chromosome X (153,902,531 to 153,907,166, forward strand). Ensembl gene ENSG00000126895.
Subcellular location: Cell membrane
Pathways (Reactome):
Signal Transduction: G alpha (s) signalling events; Vasopressin-like receptors
Vesicle-mediated transport: Cargo recognition for clathrin-mediated endocytosis; Clathrin-mediated endocytosis
Disease: Defective AVP does not bind AVPR2 and causes neurohypophyseal diabetes insipidus (NDI)
Transport of small molecules: Vasopressin regulates renal water homeostasis via Aquaporins
Gene Ontology:
Molecular function: protein binding; vasopressin receptor activity; G protein-coupled receptor activity; signaling receptor activity
Biological process: adenylate cyclase-activating G protein-coupled receptor signaling pathway; negative regulation of cell population proliferation; renal water absorption; activation of adenylate cyclase activity; adenylate cyclase-modulating G protein-coupled receptor signaling pathway; cellular response to hormone stimulus; G protein-coupled receptor signaling pathway; hemostasis; positive regulation of gene expression; positive regulation of vasoconstriction; regulation of systemic arterial blood pressure by vasopressin; renal water retention; negative regulation of urine volume; positive regulation of blood pressure; positive regulation of cell population proliferation; positive regulation of intracellular signal transduction; positive regulation of systemic arterial blood pressure; telencephalon development
Cellular component: endocytic vesicle; endosome; perinuclear region of cytoplasm; plasma membrane; clathrin-coated endocytic vesicle membrane; endoplasmic reticulum; Golgi apparatus; membrane
Homologues: Orthologues: chimpanzee AVPR2 (99% identical), macaque AVPR2 (95% identical), rat Avpr2 (88% identical), mouse Avpr2 (88% identical), dog AVPR2 (86% identical), rabbit AVPR2 (86% identical), pig AVPR2 (85% identical), guinea pig AVPR2 (83% identical), zebrafish avpr2ab (52% identical), tropical clawed frog avpr2 (51% identical), zebrafish avpr2aa (49% identical), Drosophila melanogaster CCAP-R (29% identical). Paralogues in human: AVPR1B (41% identical), OXTR (39% identical), AVPR1A (37% identical), CCKBR (23% identical), CCKAR (22% identical), GPR150 (22% identical), HCRTR1 (22% identical), HCRTR2 (21% identical), GALR1 (20% identical), GALR3 (19% identical), NPFFR1 (19% identical), GNRHR (19% identical), and 4 more.
Diseases named in the same sentence as AVPR2 in open-access papers:
AVPR2 is named in the same sentence as 114 diseases in open-access papers, as found by Europe PMC text mining. Sharing a sentence is not in itself a finding about the gene and the disease. The quoted sentences say what the papers report.
Hyponatremia (40 papers, 2010 to 2025). An abnormally decreased sodium concentration in the blood. "NSIAD is a rare X-linked condition, caused by activating mutations in the AVPR2 gene coding for the vasopressin V2 receptor (V2R) associated with hyponatremia, despite undetectable plasma vasopressin levels." (PMID 32486031, 2020). "Unfortunately, a first cousin, also having the same AVPR2 mutation, experienced several seizure episodes due to recurrent hyponatremia between 27 months and 5 years of age and eventually developed permanent mental retardation." (PMID 22518188, 2012). "A female infant with massive renal enlargement, respiratory compromise and hyponatraemia was treated with the arginine vasopressin receptor 2 antagonist tolvaptan." (PMID 28194574, 2017). "Therefore, targeting AVPR2 might have a beneficial effect both on hyponatremia, when present, and on tumor growth." (PMID 39125971, 2024). "Among the strategies used for the treatment of hyponatremia, a distinguished role has been recognized in the last fifteen years in AVP receptor type 2 (AVPR2) antagonists, the so-called vaptans." (PMID 39125971, 2024).
nephrogenic diabetes insipidus (34 papers, 2008 to 2025). Nephrogenic diabetes insipidus (NDI) is characterized by polyuria with polydipsia, recurrent bouts of fever, constipation, and acute hypernatremic dehydration after birth that may cause neurological sequelae. "We also excluded the possibility of arginine vasopressin resistance (AVP-R, previously ‘nephrogenic diabetes insipidus’) caused by a loss-of-function mutation in the arginine vasopressin receptor 2 gene (AVPR2)." (PMID 41347136, 2025). "X-linked nephrogenic diabetes insipidus (NDI) is a rare genetic renal disease caused by pathogenic variants in the AVPR2 gene." (PMID 38254165, 2024). "X-linked nephrogenic diabetes insipidus (X-linked NDI) is a rare inherited disease mainly caused by lost-of-function mutations in human AVPR2 gene encoding arginine vasopressin receptor 2 (V2R)." (PMID 34040143, 2021). "It is reported that numerous human genetic diseases were caused by single nucleotide mutation, such as the 878 G > A (AVPR2 W293X) in X-linked Nephrogenic diabetes insipidus and the 1517 G > A (FANCC W506X) in Fanconi anemia." (PMID 31057603, 2019). "Almost 90% of nephrogenic diabetes insipidus (NDI) is caused by mutations in the arginine vasopressin receptor 2 gene (AVPR2) on the X chromosome." (PMID 30073107, 2018). "It has been reported that mutations in arginine vasopressin type 2 receptor (AVPR2) cause congenital X-linked nephrogenic diabetes insipidus (NDI)." (PMID 29394883, 2018). "Disruption of the renal AVPR2/AQP2 pathway can cause nephrogenic diabetes insipidus (NDI) characterized by the inability to concentrate urine." (PMID 29117938, 2018). "Variants were additionally found in genes linked to nephrogenic diabetes insipidus type 1 (AVPR2), the SLC2A2 gene encoding the GLUT2 protein, which plays a key role in glucose metabolism, and the MAPK8IP1 gene encoding a regulator of pancreatic beta-cell function." (PMID 40149731, 2025). "This pathway can be altered by mutations in AVPR2 causing nephrogenic diabetes insipidus." (PMID 29117938, 2018). "Similarly, monogenic mutations of the PTHR1 gene is known to be involved in chondrodysplasia and multi-organ disorders, while monogenic mutants of Vasopressin receptor (AVPR2) are implicated in nephrogenic diabetes insipidus." (PMID 18452600, 2008). "Mutations of either AVPR2 or AQP2 result in a genetic disease known as nephrogenic diabetes insipidus, which is characterized by the lack of responsiveness of the collecting duct to the antidiuretic action of AVP." (PMID 29125546, 2017). "Furthermore, in vivo, intraperitoneal administration of BRL37344 triggered antidiuresis in AVPR2 conditional knockout mice, which are unable to concentrate urine in response to AVP, recapitulating the main hallmark of the rare human genetic disease X-linked nephrogenic diabetes insipidus (XNDI)." (PMID 36674662, 2023).
cyst (31 papers, 2013 to 2026). A sac-like closed membranous structure that may be empty or contain fluid or amorphous material. "METTL3 promotes cyst proliferation and new protein synthesis by enhancing c-Myc and Avpr2 mRNA m6A modification and translational activation of the cyst-promoting c-Myc and cAMP pathway via c-Myc and cAMP signaling." (PMID 38066436, 2023). "METTL3 promotes cyst proliferation by increasing the methylation and translation of arginine-vasopressin receptor 2 (AVPR2) and c-Myc mRNA, which in turn enhance cyclic adenosine monophosphate and c-Myc signaling." (PMID 37841018, 2023). "Collecting duct cyst formation is usually attributed to vasopressin-mediated activation of AVPR2, which preferentially couples with Gs to activate AC, leading to cAMP production." (PMID 35309912, 2022). "Tolvaptan, the only FDA-approved drug for inhibiting cyst dilation, targets AVPR2 in the collecting duct." (PMID 35309912, 2022).
diabetes insipidus (15 papers, 2014 to 2025). A disorder characterized by excretion of large amounts of urine, accompanied by excessive thirst. "In contrast, we have found that birds lack AVPR2, the kidney antidiuretic hormone receptor, whose loss in humans causes a genetic form of diabetes insipidus." (PMID 25518852, 2014). "Also, zebrafish models are probably unsuitable to study genetic diseases affecting water homeostasis, such as hereditary nephrogenic diabetes insipidus, which is caused by either AVPR2 or AQP2 defects in humans." (PMID 30200518, 2018). "p.H80Y mutation will cause inappropriate folding of the protein compromising water homeostasis via AVPR2 and AVP and leading to diabetes insipidus." (PMID 29991464, 2018).
heart failure (10 papers, 2013 to 2025). Inability of the heart to pump blood at an adequate rate to meet tissue metabolic requirements. "Rats with CRF–CHF experienced exacerbated renal and cardiac failure, characterized by significant disturbances in water and sodium metabolism and abnormal expression of AVPR1a and AVPR2." (PMID 39588122, 2024). "Due to the dual damage of heart failure and renal failure, CRF–CHF rats showed significant disturbances in sodium and water metabolism, and additionally, abnormal upregulation of AVPR1a and AVPR2 expression levels." (PMID 39588122, 2024).
Polyuria (10 papers, 2006 to 2023). An increased rate of urine production. "Female carriers do not usually show symptoms of NDI as observed in IV-2 and IV-4, but a small proportion of female carriers develop varying degrees of polyuria and polydipsia that can be explained by skewed inactivation of the X chromosome containing the functional AVPR2 allele." (PMID 18489790, 2008). "Therefore, the person will present polyuria if he has abnormal function or loss-of-function of AVPR2." (PMID 17101063, 2006). "However, approximately 1% of females heterozygous for an AVPR2 gene mutation may display variable degrees of polyuria and polydipsia, which has been explained by a preferential inactivation (skewing) of the X chromosome bearing the normal AVPR2 allele." (PMID 17101063, 2006). "The central role of specific AQP2 and AVPR2 in regulating water homeostasis will provide correlations in case of CKD with polyuria." (PMID 34903939, 2021).
breast cancer (9 papers, 2014 to 2023). A primary or metastatic malignant neoplasm involving the breast. "On the contrary, when AVPR1a is blocked by selective antagonists such as relcovaptan or tumor cells are exposed to specific AVPR2 agonists such as desmopressin, significant antiproliferative effects are achievable in hormone-resistant breast cancer cell lines." (PMID 31998646, 2019). "AVPR2 plays a potential role in the development of canine mammary tumors." (PMID 38155938, 2023). "To further validate the identified target genes that showed significant changes in DE and DM patterns in response to maternal BSp treatment, we evaluated gene expression of Avpr2, Cyp4a12b, Dpp6, Gria2, Pcdh9 and Tspan11 genes in the offspring mammary tumors using qRT-PCR." (PMID 35263365, 2022). "In breast cancer cells expressing AVPR1a and AVPR2, natural vasopressin can activate both receptors but its affinity is higher for AVPR1a and the number of functional AVPR2 tends to be relatively low." (PMID 31998646, 2019).
Polydipsia (9 papers, 2006 to 2024). Excessive thirst manifested by excessive fluid intake. "Here, we identify and functionally characterize a novel AVPR2 missense mutation found in a woman with a history of polyuria and polydipsia." (PMID 35055433, 2022). "Herein, we report a rare case of CNDI caused by an AVPR2 mutation in a 2-year-old Chinese boy who had sustained polyuria, polydipsia, and irritability for more than 20 months." (PMID 34336746, 2021). "X‐linked nephrogenic diabetes insipidus (X‐NDI) is a rare congenital disease caused by inactivating mutations of the vasopressin type‐2 receptor (AVPR2), characterized by impaired renal concentrating ability, dramatic polyuria, polydipsia and risk of dehydration." (PMID 38652212, 2024). "Most female carriers of AVPR2 heterozygosity remain asymptomatic; however, a small subset experiences varying degrees of polyuria and polydipsia." (PMID 39474227, 2024). "Ten boys from nine families were identified with mutations in AVPR2 or AQP2 along with dehydration, polyuria–polydipsia, and severe hypernatremia." (PMID 33996673, 2021).
chronic heart failure (6 papers, 2013 to 2024). "Patients with congestive heart failure face similar fluid retention challenges, and congestive heart failure has been strongly associated with both AVPR2 and NPR1 genes." (PMID 39148855, 2024). "TXGNN Explainer suggested that the relationship between NSIAD and amyl nitrite passes through AVPR2, congestive heart failure, and NPR1." (PMID 39148855, 2024).
Hypertension (5 papers, 2017 to 2025). The presence of chronic increased pressure in the systemic arterial system. "CKD was a chronic disease characterized by hypertension, urinary concentrating abnormalities, and electrolyte imbalances which including polyuria, hypercalcemia, hypernatremia, and hypokalemia caused by changes in AQP2 and AVPR2 expression." (PMID 34903939, 2021).
chronic kidney disease (4 papers, 2021 to 2025). Impairment of the renal function secondary to chronic kidney damage persisting for three or more months. "This study was to investigate the abnormalities in water and sodium metabolism, as well as the expression levels of arginine vasopressin receptor 1a (AVPR1a) and arginine vasopressin receptor 2 (AVPR2), in a rat model of chronic renal failure–chronic heart failure (CRF–CHF)." (PMID 39588122, 2024).
Obesity (4 papers, 2016 to 2025). Accumulation of substantial excess body fat. "This, in part, may suggest a potential link between obesity and nephrogenic diabetes in the context of AVPR2 gene mutations." (PMID 40149731, 2025).
polycystic kidney disease (4 papers, 2016 to 2025). A usually autosomal dominant and less frequently autosomal recessive genetic disorder characterized by the presence of numerous cysts in the kidneys leading to end-stage renal failure. "Thus, this pathway may constitute a valid alternative for the treatment of conditions characterized by impairments in vasopressin signaling or vasopressin type 2 receptor (AVPR2) expression, such as NDI, polycystic kidney disease (PKD), or the syndrome of inappropriate secretion of AVP (SIADH)." (PMID 30995798, 2019).
renal carcinoma (4 papers, 2020 to 2024). A carcinoma arising from the epithelium of the renal parenchyma or the renal pelvis. "Similarly, an additional study demonstrated opposite effects of dDAVP and satavaptan, another AVPR2 antagonist, in renal cancer cell lines." (PMID 39125971, 2024).
colorectal cancer (3 papers, 2017 to 2022). A primary or metastatic malignant neoplasm that affects the colon or rectum. "The arginine vasopressin type 2 receptor (AVPR2) agonist was able to impair tumor aggressiveness and distant spread in colorectal cancer." (PMID 36032660, 2022).
renal cell carcinoma (3 papers, 2021 to 2023). "AVPR2 is associated with immune cell infiltration in renal cell carcinoma." (PMID 36998036, 2023). "The expression level of AVPR2 in renal cell carcinoma was significantly lower than that in normal tissues, and a high expression level of AVPR2 was associated with a better prognosis." (PMID 36998036, 2023). "The expression of AVPR2 has been reported in a variety of cancers, including osteosarcoma, renal cell carcinoma, breast cancer, pancreatic cancer, colorectal cancer, and small cell lung cancer." (PMID 36998036, 2023). "Activation of arginine vasopressin receptor 2 (V2R) by arginine vasopressin (AVP) stimulates the cell proliferation of renal cell carcinoma (RCC)." (PMID 35011543, 2022).
renal failure (3 papers, 2017 to 2024). "It is difficult to find information about the influence of soy isoflavones on AQP2 or AVPR2 in the literature, but there is information about other natural compounds such as triterpenoids that have been shown to downregulate renal AQP2 to protect against renal failure." (PMID 38791455, 2024).
type 2 diabetes (2 papers, 2024 to 2025). "Results unveiled notable alterations in water intake, body and kidney mass, kidney morphology, fatty acids, AQP2, AVPR2, AcetylCoA, SREBP-1, blood urea, creatinine, and glucose levels in control rats with induced type 2 diabetes." (PMID 38791455, 2024).
ACTHomas (1 paper, 2020). "In addition to the impaired glucocorticoid negative feedback, ACTHomas exhibits increased or aberrant expression of AVPR1b or AVPR2, which is associated with a paradoxical response to DDAVP." (PMID 33266265, 2020). "As normal corticotrophs express lower levels of AVPR1b, and intra-venous DDAVP injection does not stimulate ACTH secretion in patients who do not have ACTHomas, AVPR1b or AVPR2 has been shown to express abundantly in ACTHomas." (PMID 33266265, 2020).
adenoma (1 paper, 2013). A neoplasm arising from the epithelium. "Expression of mRNA of vasopressin receptors (AVPR1A, AVPR2, AVPR1B) was studied in a panel of adrenocortical tissues, consisting of AIMAH, normal adrenals, ACTH-dependent hyperplasias, adenomas and carcinomas." (PMID 24034279, 2013).
breast tumors (1 paper, 2022). "The results in our study also thereby identified Avpr2 as a key transcript which was upregulated and hypomethylated in offspring breast tumors with maternal BSp treatment." (PMID 35263365, 2022).
Cushing syndrome (1 paper, 2023). Cushing's syndrome (CS) encompasses a group of hormonal disorders caused by prolonged and high exposure levels to glucocorticoids that can be of either endogenous (adrenal cortex production) or exogenous (iatrogenic) origin. "The gene AVPR2 has been found to be overexpressed in Cushing syndrome andcorticotropic tumors, affecting hormone levels and leading to changes in cell growthand function." (PMID 37930141, 2023).
head and neck cancer (1 paper, 2022). A primary or metastatic malignant neoplasm affecting the head and neck. "A study reported that Avpr2 was associated with G-protein-couple-receptor signaling pathway wherein the transcript was found to be upregulated 2-fold in squamous cell carcinoma causing overexpression of miR-10b profile in head and neck cancer." (PMID 35263365, 2022).
head and neck squamous cell carcinoma (1 paper, 2023). A squamous cell carcinoma that arises from any of the following anatomic sites: lip and oral cavity, nasal cavity, paranasal sinuses, pharynx, larynx, and salivary glands. "To validate the AVPR2 expression results from public databases, we evaluated the expression of AVPR2 in head and neck squamous cell carcinoma tissues and paracarcinoma tissues by IHC." (PMID 36998036, 2023).